NRP2 (neuropilin 2)
Diseases named in the same sentence as NRP2 in open-access papers (continued):
Sharing a sentence is not in itself a finding about the gene and the disease.
tumor (continued). "Lastly, we generated an orthotropic xenograft tumor model to identify the pro-angiogenic effect of NRP2 in vivo." (PMID 32983407, 2020). "NRP2 is highly expressed in lymphatic ECs and in the stroma of many types of tumour, where it supports lymphangiogenesis and neovascularisation." (PMID 32708258, 2020). "Coexpression of the NRP1 and NRP2 genes has been reported to be significantly correlated with tumor progression through neovascularization in NSCLC41." (PMID 32678190, 2020). "Here, we show that tumor angiogenesis triggered by vascular NRP2 is driven by the promotion of F-actin polymerization in HUVECs." (PMID 32983407, 2020). "NRP2 sialylation reduces phagocytosis capacity of the macrophages, thus NRP2+ M2 macrophages promote tumor progression." (PMID 32766254, 2020). "Blocking NRP2 in vivo suppressed PNET angiogenesis and tumor growth, and elevated NRP2 expression was associated with poor prognosis in PNET patients." (PMID 32983407, 2020). "Taken together, NRP2 supports a vast number of tumor-promoting events but seems to be less crucial in most healthy tissues, and thus, it has become an attractive target for anti-cancer therapy." (PMID 32038994, 2019). "Further studies confirmed that the inhibitory activity of Sema3F on GBM cell migration depends on NRP2 expression, suppressed by hypoxia in the tumor context, and on the subsequent RhoA inactivation." (PMID 31052281, 2019). "While SEMA3C inhibits tumor lymphangiogenesis and metastasis, its furin-cleaved form p65-SEMA3C has tumor-promoting properties in NRP2-expressing cancer cells, which was found at least in vitro, however, not yet in vivo." (PMID 30717262, 2019). "This tumor-suppressing effect induced by either local or systemic administration of Sema3F was attributed to Sema3F/NRP2-mediated inhibition of Akt-mTOR signaling." (PMID 31052281, 2019). "In contrast, loss of miR-331-3p expression contributes, at least in part, to tumor growth and progression through upregulation of NRP2, and consequently increased proliferation and clonogenic growth." (PMID 30717262, 2019). "Both neuropilins, i.e., neuropilin-1 (NRP1) and neuropilin-2 (NRP2), are overexpressed in various cancer types and their expressions have been correlated with tumor progression and poor prognosis." (PMID 31664117, 2019). "VEGF/NRP2 in combination with α6β1 facilitates the FAK-RAS signaling pathway activation that contributes to tumor de-differentiation and initiation." (PMID 30871059, 2019). "Most prominent was the effect in the NRP2 knockdown group, with a >45% reduction in tumor size at day 25 after the initiation of treatment." (PMID 31664117, 2019). "Various possibilities for the interaction of integrins with NRPs have been discussed: An intercellular interaction between integrins α5β1 and α9β1 on cancer cells with NRP2 as counterreceptor on ECs enhances tumor cell spreading and metastasis." (PMID 30717262, 2019). "Human NSCLC were also found to express NRP2, such as tumour samples 1, 3 and 8, and certain Plexin (Plxn) A or D family member transcripts, as well as genes encoding Nrp ligands of the Sema-3 family, such as Sema-3B, -3C, -3E and -3F." (PMID 31350404, 2019). "The same was true of Sema3F, which interacts with NRP2 and inhibits tumor formation and angiogenesis." (PMID 31052281, 2019). "NRP2 signaling in pancreatic adenocarcinoma promotes tumor angiogenesis by increasing Jagged1 levels." (PMID 30717262, 2019). "The VEGFR family includes VEGFR-1(Flt-1), VEGFR-2(KDR/Flk-1), VEGFR-3(Flt-4), NRP-1 and NRP-2 with VEGFR-2 is supposed to be closer to generation of tumor vessels." (PMID 29662638, 2018). "We profiled levels of phosphokinases in NRP2-expressing tumor cells to determine the inhibitory effect of SEMA3F." (PMID 30532711, 2018).
tumor (continued). "Outside of the tumor environment, NRP‐2 is normally expressed in lymphatic vessels during embryogenesis." (PMID 30216699, 2018). "Nrp2 inhibition in a cellular mouse model of SHH MB decreased tumor growth both in vitro and in vivo and the consequent mortality." (PMID 30483126, 2018). "Taken together, VEGF and its subtype VEGF-C, VEGF receptors (VEGFR) and their signaling pathways NRP-2 play vital roles in developing tumor and lymphangiogenesis." (PMID 29861465, 2018). "Tumor-induced activation of neuropilin-2 on lymphatic endothelial cells can increase peritumoral lymphangiogenesis and promote lymph node metastasis." (PMID 29017512, 2017). "This suggests that NRP2 has a role in normal bone homeostasis, which is particularly important in cancer patients where tumor metastasis to bone can result in deregulation of normal homeostasis process." (PMID 29067024, 2017). "Neuropilin-2 on tumor cells interacts with integrins on blood and lymph vessel endothelial cells to mediate vascular adhesion and promote extravasation." (PMID 29017512, 2017). "Consistently, upregulation and/or mislocalisation of NRP1 and NRP2 to the basolateral region correlates with invasiveness and poor prognosis in a number of tumour types." (PMID 28062852, 2017). "M2 macrophages and maturing monocytes under prolonged hypoxia can produce VEGF, which is also a ligand for NRP-1 and NRP-2, and can thus promote tumor progression and angiogenesis." (PMID 26900851, 2016). "The expression of SEMA 3F clearly decreased with tumor stage, whereas that of its main receptor neuropilin-2 (NRP-2) slightly increased with tumor stage." (PMID 26447612, 2015). "NRP2 modulates tumor blood vessel formation by altering the recruitment of endothelial cells to OS tumor cells." (PMID 25890345, 2015). "In vivo, local and systemic overproduction of SEMA3F reduces tumor growth in NRP2-expressing xenografts." (PMID 26156437, 2015). "We employed a tissue array containing 133 HCC cases for the analysis of NRP2 expression and found a significant correlation of NRP2 levels with higher tumor grading." (PMID 26573807, 2015). "In accordance with these data, elevated levels of NRP2 correlated with a higher tumor grade and less differentiation in a large collection of human HCC specimens." (PMID 26573807, 2015). "Many malignant tumor cell lines express NRP2 and this appears to contribute to their aggressiveness." (PMID 26030152, 2015). "In cancer patients, expression of NRP1, NRP2 or both NRPs is often upregulated and is correlated with tumor aggressiveness and advanced disease stage." (PMID 26030152, 2015). "Given the implication of NRP2 in tumor growth, angiogenesis, and metastasis, understanding the regulation of NRP2 expression is of importance." (PMID 25890345, 2015). "We demonstrated that inhibition of NRP2 expression by shRNA knockdown impaired tumor growth, invasion, and blood vessel formation in OS." (PMID 25890345, 2015). "By knocking down NRP2 using ShRNA, we examined the potential role of NRP2 in modulating tumor growth, invasion, metastasis and blood vessel formation in OS." (PMID 25890345, 2015). "In this study, we examined the expression of NRP2 in OS cell lines and tumor tissues, and correlated the expression levels with patients’ survival." (PMID 25890345, 2015). "In breast, colorectal and pancreatic cancer, blocking NRP-2 resulted in suppressed tumor growth, reduced lymphangiogenesis/angiogenesis and metastasis, although the underlying mechanisms are still poorly understood." (PMID 25890345, 2015). "Combined, SEMA3F/NRP2 signaling represents an important regulatory axis in tumor lymphangiogenesis, thus providing new therapeutic targets to halt aggressive metastasis." (PMID 26319580, 2015).
tumor (continued). "We demonstrate that Nrp2 is the VEGF-C-associated receptor that mediates alterations in Sod3 expression and the response of tumor cells to oxidative stress." (PMID 25358638, 2014). "The capacity for miR-331-3p to regulate NRP-2 expression is of interest given a number of recent reports that emphasize the importance of NRP-2 in tumor growth and progression, and as a promising therapeutic target." (PMID 24142150, 2014). "Taken together, these findings suggest that miR-331-3p acts as a tumor suppressor in the brain by coordinately inhibiting expression of multiple target molecules, including NRP-2 and DOHH, leading to reduced GBM cell proliferation and clonogenic growth." (PMID 24142150, 2014). "Depletion of NRP2 in TBP tumour cells using shRNA significantly attenuated their ability to form tumours in mice." (PMID 23436775, 2013). "As in developmental lymphangiogenesis, transcription factors Sox18 and COUP-TFII and the VEGF-C/VEGFR-3/Nrp2 system are utilized by tumor cells to regulate LEC differentiation and lymphatic vessel sprouting, respectively." (PMID 24286034, 2013). "The mechanism by which NRP2 signalling promotes tumour initiation involves stimulation of the α6β1 integrin, focal adhesion kinase-mediated activation of Ras/MEK signalling and consequent expression of the Hedgehog effector GLI1." (PMID 23436775, 2013). "Although our study affirms the importance of autocrine VEGF/NRP signalling in tumour initiation, it is the first such study to implicate NRP2." (PMID 23436775, 2013). "A critical result supporting this conclusion is that NRP2 inhibition delayed the onset of tumours in a mouse model of TNBC." (PMID 23436775, 2013). "Our data reveal a novel autocrine signalling pathway mediated by VEGF/NRP2 and α6β1 signalling that contributes to tumour initiation." (PMID 23436775, 2013). "A significant increase in tumour-free survival was observed in NRP2-depleted cells compared to control cells providing evidence for the importance of NRP2 in GLI1-mediated tumourigenesis." (PMID 23436775, 2013). "To establish the role of GLI1 in NRP2-mediated tumour initiation, we expressed GLI1 in the SUM1315 NRP2low cells and assayed their ability to form orthotopic tumours." (PMID 23436775, 2013). "Expression of GLI1 decreased the incidence of tumour-free survival significantly demonstrating that GLI1 is sufficient to compensate for low NRP2 expression in tumour initiation." (PMID 23436775, 2013). "The role of NRP2-mediated Ras activation in tumour initiation is supported by the finding that expression of a constitutively-active Ras construct in NRP2low SUM1315 cells promoted tumour formation." (PMID 23436775, 2013). "Based on the findings that NRP2 plays an important role in tumour initiation, we evaluated the potential of a function-blocking NRP2 Ab (Anti-Nrp2B) to impact established tumours." (PMID 23436775, 2013). "To establish the role of NRP2 in tumour initiation more definitively, we injected TBP mice with a NRP2 inhibitory Ab (Anti-Nrp2B) at the time of pregnancy, which triggers tumour onset in this transgenic model." (PMID 23436775, 2013). "We discovered the VEGF receptor neuropilin-2 (NRP2) is expressed preferentially on TICs, involved in the genesis of TNBCs and necessary for tumour initiation." (PMID 23436775, 2013). "The involvement of NRP2 in tumour initiation was evaluated in vivo using the NRP2high and NRP2low populations sorted from SUM1315 cells." (PMID 23436775, 2013). "Many malignant tumor cell lines express Nrp1 and/or Nrp2, and this appears to contribute to their aggressiveness." (PMID 22948112, 2012). "Targeting Nrp-2 therefore has been considered as a potential way to block tumor spread via inhibition of neo-lymphangiogenesis." (PMID 22481918, 2012). "NRP-1 and NRP-2 are expressed in several types of tumour cells; in many cancers the expression of one or both has been correlated with tumour progression and/or poor prognosis." (PMID 23185562, 2012).
tumor (continued). "To examine the effect of NRP2 expression on in vivo tumor growth, we inoculated equal numbers (1.106 cells per mouse) of HT29NRP2 or HT29ctrl subcutaneously into nude mice." (PMID 21747928, 2011). "More recent studies from our laboratory have focused on the role of the VEGF co-receptor, neuropilin-2 (NRP-2), which mediates tumour cell survival pathways." (PMID 21407219, 2011). "Nrp2 was also detected in salivary adenoid cystic carcinomas (SACCs), and its expression level significantly correlated with microvessel density, tumor size, clinical stage, vascular invasion, and metastasis of SACCs." (PMID 24212788, 2011). "By blocking binding of VEGF and VEGFC to NRP2, these anti-NRP2B monoclonal antibodies decrease the number of tumor-associated lymphatic vessels and metastasis in sentinel lymph node and in distant organs in mice xenograft experiments." (PMID 24212788, 2011). "Collectively, our results demonstrate that tumor cell–derived NRP-2 mediates critical survival signaling in gastrointestinal cancer cells." (PMID 22028766, 2011). "(i) It is conceivable that in tumor cells increased expression of NRP2 on the cell surface results in ligand-independent activation of NRP2 mediated signaling through spontaneous NRP2 binding to VEGFR/plexin." (PMID 22028766, 2011). "Conversely, NRP2 knockdown using specific siRNA, negatively modulated the proliferation of Colo320 tumor cell line." (PMID 21747928, 2011). "Immunohistochemical staining of tumor tissues confirmed that NRP-2 expression was reduced in the tumors from mice treated with NRP-2 siRNA-DOPC sequences compared with tumors from mice treated with cntr siRNA-DOPC sequences." (PMID 22028766, 2011). "Although the expression of NRP-2 was originally thought to be limited to neurons, studies have shown that NRP-2 is expressed on VSMCs, endothelial cells, and tumor cells." (PMID 22028766, 2011). "Analysis of NRP2 transfected cell lines and NRP2 expressing xenografts established that NRP2-expressing tumor cells displayed an immunohistochemical phenotype of EMT characterized by the loss of E-Cadherin and an increase of vimentin expression." (PMID 21747928, 2011). "We took advantage of the previous cell lines to study the role of NRP2 on cancer proliferation in vitro and tumor growth in vivo." (PMID 21747928, 2011). "Coexpression of NRP1 and NRP2 also increases in the progression from dysplasia to microinvasive lung carcinoma, and correlates significantly with tumour progression and poor prognosis in patients with non-small-cell lung carcinoma." (PMID 20087344, 2010). "For a shorter time of tea fermentation, the low dosage consumption of white tea in BC-induced rat models demonstrated anti-inflammatory effects, lipid peroxidation and DNA damage prevention, apoptosis-induced tumor suppression, and NRP-2 activity and M-CSF release inhibition." (PMID 40427676, 2025). "Disruption of this NRP2 axis restores antitumor immunity and curtails tumor growth." (PMID 41355895, 2025). "If NRP2 is deleted, efferocytotic clearance of apoptotic tumour cells is impaired and secondary necrosis leads to activation of a more effective anti-tumour immune response, highlighting the importance of tumour modulation of the NRP molecular switch in TAMs for disease progression." (PMID 40134439, 2025). "However, the shared structures and ligands (VEGFR1, NRP1, NRP2 and heparin) present opportunities to identify antibodies with dual-specificity to block both growth factors and thereby limit a mechanism of tumor resistance." (PMID 41306516, 2025). "We also observed an overexpression of Neuropilin-2 (NRP2) in tumor tissue." (PMID 40522948, 2025). "NRP1-mediated angiogenesis in ccRCC and NRP2-driven lymphangiogenesis and tumor invasion in SKCM demonstrate the complexity of TME dynamics, and their shared role in ECM remodelling and cancer immune evasion provides novel insights into effector mechanisms of M2-polarised macrophages in the TME." (PMID 40134439, 2025).
tumor (continued). "In contrast, NRP-2 has been connected with increased tumor metastasis and poor prognosis, showing that it may also be a valuable therapeutic target." (PMID 40430075, 2025). "Additionally, depletion of NRP2 from TAMs impaired the clearance of apoptotic tumour cells and increased secondary necrosis within tumours." (PMID 40134439, 2025). "In this study, we firstly revealed that the level of some proteins (such as NRP2, TIMP1, ITGB2, ITGAM) associated with tumor metastasis promotion was decreased in the exosomes derived from MNDA knockdown M2 macrophages, which could be taken up by HCC cells." (PMID 38904028, 2024). "We investigated these approaches in our animal models using VEGF/NRP2 function-blocking mAbs and observed enhanced radiosensitivity that resulted in regression in tumor growth and increased necrosis using single-dose, conventional fractionation, and hypofractionated radiation." (PMID 39352757, 2024). "Importantly, treatment of patient-derived xenografts with the NRP2 mAb and radiation resulted in significant tumor necrosis and regression compared with radiation alone." (PMID 39352757, 2024). "Depletion of Nrp2 in TAMs (Nrp2fl/flCSF1R-iCre) inhibited efferocytosis and transcription of anti-inflammatory factors IL-10, IL-4, TGFβ, PD-L2 while promoting IL-12 and IFNβ expression, collectively slowing tumor growth in mouse pancreatic cancer." (PMID 38592275, 2024). "NRP2 regulates lymphatic vessel growth and promotes tumor metastasis to the lymphatic pathways." (PMID 37745301, 2023). "As an independent receptor or a co-receptor, Nrp2 binds to ligands VEGF-C/D, activates the VEGF-C/D-Nrp2 signaling axis, and further regulates lymphangiogenesis-associated factors in both lymphatic endothelial cells (LECs) and tumor cells." (PMID 35158941, 2022). "NRP1flflNRP2flfl.ECKO PyMT-BO1 tumors were found to be approximately 70% less vascularized than respective Cre-negative control tumors, corroborating our CMT19T studies, and confirming that the expression of NRP1 and NRP2 is essential for tumor angiogenesis in multiple cancer models." (PMID 36970722, 2022). "Utilizing these models, we demonstrate that in multiple models of cancer, cotargeting the endothelial expression of both NRP1 and NRP2 severely inhibits primary and secondary tumor growth and angiogenesis, to a much greater extent than when either NRP receptor is targeted alone." (PMID 36970722, 2022). "Either NRP-1 or NRP-2 or both are expressed in nearly all tumor cells." (PMID 35052853, 2022). "Nrp2 is a key regulator of lymphangiogenesis, including tumor lymphangiogenesis." (PMID 35158941, 2022). "Specifically, it has been described that SEMA3F could inhibit tumor growth and angiogenesis after binding with NRP2 in diverse human cell types." (PMID 35565388, 2022). "In addition, NRP2 has been found to be involved in tumour development through a variety of novel pathways." (PMID 36172369, 2022). "Among these genes, NRP2 has been most intensively studied in tumours." (PMID 36172369, 2022). "We demonstrate that the endothelial-specific cotargeting of both NRP receptors, NRP1 and NRP2, provides effective inhibition against tumor growth and secondary site metastasis in multiple cancer models, likely by potentiating the rapid delivery of VEGFR-2 to late-endosomes for degradation." (PMID 36970722, 2022). "Here, we employed murine CRC tumor-derived mesenchymal-like organoids to induce Nrp2 depletion." (PMID 35158941, 2022). "In addition to the increased risk of lymphatic metastasis, high NRP2 and low SEMA3F expression has been associated with an increase in tumor aggressiveness, evidenced as an increase in the capacity for proliferation and infiltration." (PMID 35565388, 2022). "NRP2 inhibits osteoclast activity and promotes the tumor burden in bone with mixed lesions." (PMID 35159353, 2022).